MYC (MYC proto-oncogene, bHLH transcription factor)
Diseases named in the same sentence as MYC in open-access papers (continued):
Sharing a sentence is not in itself a finding about the gene and the disease.
B-cell lymphoma (continued). "However, similar protection is not observed in AID-deficient λc-MYC and λc-MYC Iμ-HABCL6 mice, which develop pregerminal and postgerminal center B-cell lymphomas." (PMID 37600817, 2023). "Taken together, SC-1 carries three major rearrangements resulting in the gene fusions IGH::BCL2, IGH::MYC, and MBNL1::BCL6 which were characterized cytogenetically, genomically, and at the transcript level, thus, representing an exceptionally well characterized triple-hit B-cell lymphoma cell line." (PMID 37371852, 2023). "In these studies, the histology-related inclusion criteria were different; in general, the studies included high-grade B-cell lymphoma (HGBCL) with or without translocations of MYC and BCL2 and/or BCL6 (double/triple-hit lymphoma) and transformed follicular lymphoma (tFL)." (PMID 36561713, 2022). "If MYC regulates CD24 expression directly, CD24 may be one of the surrogate markers of mature B‐cell lymphoma with MYC aberrations including HGBL and ‘double expressor’ B‐cell lymphoma." (PMID 35289116, 2022). "The cases described in the current series may rather represent a distinct subset of MYC-negative unclassifiable high-grade B-cell lymphomas." (PMID 33816589, 2021). "Furthermore, data from large B-cell lymphoma patient datasets revealed a correlation of MYC and CXCR4 expression and an increase of CXCR4 expression in patient samples with translocation of MYC further supporting a regulation of CXCR4 by MYC in a B-cell oncogenic context." (PMID 34363012, 2021). "Special emphasis was laid on this group of aggressive B-cell lymphomas in recognition of its complicated classification due to the concurrence of features of both Burkitt lymphoma (BL) and diffuse large B-cell lymphoma (DLBCL) including cytogenetic aberrations affecting MYC, BCL2 and/or BCL6." (PMID 33672644, 2021). "As an example of MYC-independent targeting, genome-wide analysis of JQ1-induced transcriptional response in MYC-driven B-cell lymphoma revealed reduced BRD4 occupancy at the IFNγ PD-L1 ligand Cd274 without affecting MYC occupancy, resulting in a reduction of the CD274 mRNA level." (PMID 30906568, 2019). "In conclusion, the results of our study confirm that R-CHOP is not an appropriate therapeutic choice for “high-grade B-cell lymphoma with MYC and BCL2/BCL6 rearrangements”, and that intensive regimens or DA-EPOCH-R should be preferred, especially for younger patients." (PMID 31976479, 2019). "However, molecular studies show that a small group of B cell lymphoma reminiscent of BL without MYC translocation carries the same GEP signature than BL." (PMID 26416427, 2015). "MYC translocation-negative Burkitt lymphoma, similarly to other aggressive B-cell non Hodgkin’s lymphomas, may represent a model to understand the intricate molecular pathway responsible for MYC dysregulation in cancer." (PMID 26453442, 2015). "Since the regulatory mechanism of miR-15a/16-1 was further demonstrated in BL, it is conceivable that the c-MYC-induced miR-15a/16-1 changes by HDAC may be a novel mechanism for MYC-driven miRNA suppression and malignant transformation in aggressive B-cell lymphoma." (PMID 25232701, 2014). "MYC translocation is a defining feature of Burkitt lymphoma but is not specific, as it may also occur in other B-cell lymphomas." (PMID 24887414, 2014). "However, mutations within the c-MYC protein, although not a prerequisite for rendering c-MYC oncogenic, have also been observed in a fraction of human B-cell lymphomas." (PMID 24130880, 2013). "In addition, there are also MYC-translocation-negative aggressive B-cell lymphomas with features intermediate between BL and DLBCL." (PMID 22548066, 2012).
B-cell lymphoma (continued). "However, it is important to note that MYC translocations are not specific to Burkitt lymphoma and may also be seen in other high-grade B-cell lymphomas." (PMID 41561748, 2025). "As illustrated in case 2, the detection of IGL::MYC by GPM provides further support to a diagnosis of Burkitt lymphoma, originally favored as high-grade B-cell lymphoma due to cytomorphologic variation and the absence of IGH::MYC." (PMID 41374977, 2025). "BCL2 and/or MYC rearrangements are absent and aggressive B-cell lymphomas with IRF4 rearrangement, harboring also MYC and/or BCL2 rearrangements, are excluded from this entity." (PMID 39684922, 2024). "This entity does not include aggressive B-cell lymphomas with IRF4 rearrangements that also harbor BCL2 and/or MYC rearrangements." (PMID 36460764, 2023). "These new data, together with the absence of the IGH::MYC rearrangement, suggest that HG/LBCL-11q represents a different mature aggressive B-cell lymphoma." (PMID 37555980, 2023). "MYC can bind and activate the CXCR4 promoter, but this connection has not been explored in B-cell lymphoma so far." (PMID 34363012, 2021). "Here we describe the impact of MYC in three types of aggressive B-cell non-Hodgkin lymphomas: BL and DLBCL with and without MYC break (DLBCLneg and DLBCLpos, respectively)." (PMID 30953469, 2019). "High-grade B-cell lymphoma, NOS includes blastoid-appearing large B-cell lymphomas and cases lacking MYC and BCL2 or BCL6 translocations." (PMID 31484540, 2019). "We detect EZH2 mutations in a significant proportion of BCL2-rearranged follicular lymphomas, BCL2-rearranged diffuse large B cell lymphomas, and high-grade B cell lymphomas with concurrent BCL2 and MYC rearrangements (so-called “double-hit lymphomas”), but not in BL." (PMID 22194861, 2011). "Although high-grade B-cell lymphoma (HGBCL) prevalence showed no significant racial differences (p = 0.16), the Asian group exhibited a higher proportion of aggressive HGBCL with concurrent IGH::MYC and IGH::BCL2 fusions compared with the White group (p = 0.076)." (PMID 41301875, 2025).
Burkitt lymphoma (559 papers, 2006 to 2026). A rare form of malignant mature B-cell non-Hodgkin lymphoma. "Background and Clinical Significance: Burkitt lymphoma is an aggressive form of non-Hodgkin lymphoma of B-cell origin, caused by a MYC gene translocation on chromosome 8." (PMID 42029451, 2026). "MYC overexpression is a hallmark of Burkitt lymphoma and drives tumor growth through dysregulation of cellular metabolism." (PMID 41180747, 2025). "In line with our findings, overexpression of c-MYC, an important oncogene playing a key role in Burkitt lymphoma, has previously been associated with poorer prognosis in patients with DLBCL33." (PMID 40461625, 2025). "Burkitt lymphoma (BL), an aggressive subtype linked to MYC oncogene activation, is associated with Epstein–Barr virus (EBV) in endemic cases." (PMID 40801653, 2025). "PVT1 is closely located in the genome to the MYC gene, an universal amplifier of transcription associated with e.g. leukaemia or Burkitt lymphoma." (PMID 38384455, 2024). "Among these, the association between EBV and Burkitt lymphoma (BL) is striking, involving a tumor where MYC is deregulated by translocation in all cases." (PMID 39766110, 2024). "A translocation leading to MYC overexpression drives oncogenesis in all Burkitt lymphomas, but half of them exhibit additional missense MYC mutations enhancing its tumorigenicity." (PMID 39298333, 2024). "For example, activation of the proto-oncogene c-MYC via chromosomal translocation is a hallmark of Burkitt’s lymphoma." (PMID 39514105, 2024). "The MYC-induced lncRNA MINCR is a newly identified lncRNA linked to MYC expression in the Burkitt lymphoma." (PMID 36741910, 2023). "One such cofactor is the chromatin regulator WDR5, which in models of Burkitt lymphoma facilitates recruitment of the c-MYC protein to chromatin at genes associated with protein synthesis, allowing for tumor progression and maintenance." (PMID 37336886, 2023). "The MYC proto-oncogene, encoding the MYC transcription factor, was first identified in patients with Burkitt’s lymphoma." (PMID 38125876, 2023). "In Burkitt’s lymphoma, a homozygous single amino acid substitution in the transactivation domain of MYC was found to cause a missense mutation in two-thirds of the cell lines and biopsies examined decades ago." (PMID 37443779, 2023). "The MYC gene was initially detected in Burkitt lymphoma as a potent oncogene and is associated with aggressive clinical behavior." (PMID 35626262, 2022). "This was shown for the genes that are usually involved in chromosomal translocations that cause Burkitt’s lymphoma: MYC, IGH, IGL, and IGK, where they share a common translocation factory." (PMID 36291894, 2022). "MYC depletion resulted in increased expression of BZLF1 and BMRF1 in Akata and P3HR-1 cells, while eliminating MYC caused an increase in the expression of the late protein gp350 in Burkitt lymphoma cells." (PMID 34572593, 2021). "The main characteristic of a Burkitt lymphoma is an increased production of the MYC oncoprotein caused by chromosomal rearrangements." (PMID 33611854, 2021). "In Burkitt lymphoma itself, c-MYC deregulations, such as translocations and mutations, is highly characteristic." (PMID 34947882, 2021). "The genetic hallmark of Burkitt’s lymphoma (BL) is a MYC-IGH fusion resulting from translocations between chromosomes 8 (Myc) and 14 (IGH)." (PMID 33802828, 2021). "MYC point mutations in the coding regions are another type of genetic aberration (e.g., in a majority of the Burkitt’s lymphomas)." (PMID 32549409, 2020). "MYC mutations have been related to Burkitt’s lymphoma and leukemia; they are activated through gene rearrangement and gene amplification, which affect other genes." (PMID 33142921, 2020). "Burkitt lymphomas have a mutation in the MYC gene and this mutation is associated with EBV activation of B-cells." (PMID 32431983, 2020).
Burkitt lymphoma (continued). "JQ1, iBET, and bromodomain inhibitors selectively bind to the domains of BRD4,78,79 which causes selective repression of the MYC oncogene in a wide range of tumors including multiple myeloma (MM), Burkitt’s lymphoma (BL), AML, and ALL60–63,80." (PMID 32128448, 2020). "More recently, a second hotspot of tumour-associated MYC mutations was identified in codons 243–249 through meta-analysis of mutation data from Burkitt lymphoma." (PMID 31844144, 2020). "Translocations of MYC were first associated with Burkitt lymphoma, but it has since been found that MYC recombination with other genes is reported in 3–16% of DLBCL cases." (PMID 33216822, 2020). "In another study, knockdown of PVT1 inhibited the proliferation of Burkitt lymphoma cells by arresting the cells in G0/G1 phase which was associated with a reduction of MYC expression and alterations in the expression of cell cycle-associated genes." (PMID 33134177, 2020). "Shedding light on how MYC controls DNA methylation in T-ALL and Burkitt lymphoma, we recently reported that MYC causes the overexpression of DNMT3B, maintaining specific 5mC and thus gene expression patterns which are important for tumor maintenance." (PMID 31266538, 2019). "Burkitt lymphoma is a highly aggressive mature B-cell lymphoma commonly associated with translocation of MYC gene." (PMID 32117783, 2019). "The localization of MYC proto-oncogene on q24 of the human chromosome 8 and its translocation to chromosome 14 is considered pathogenic in most cases of Burkitt lymphoma." (PMID 32117783, 2019). "Together, our results show that 17-DMAG decreased tumor cell proliferation and reduced MYC mRNA and protein expression, ultimately causing cell cycle arrest, necrosis and apoptosis in Burkitt lymphoma cell lines." (PMID 30453475, 2018). "We found that suppression of MYC in Burkitt lymphoma upon HSP90 inhibition was associated with an increase in G0/G1 cell cycle arrest, and an increase in necrotic and apoptotic cells." (PMID 30453475, 2018). "Together, our results show that 17-AAG decreased tumor cell proliferation and reduced MYC mRNA and protein expression, subsequently causing both cell cycle arrest and apoptosis in Burkitt lymphoma cell lines." (PMID 30453475, 2018). "Burkitt lymphomas are characterized by constitutive MYC expression caused by one of three chromosomal translocations, placing MYC under control of the immunoglobulin heavy chain (IgH) enhancer." (PMID 30453475, 2018). "Here, we report that in T-ALL and Burkitt’s lymphoma MYC directly caused the overexpression of both DNMT1 and DNMT3B." (PMID 29100357, 2017). "In human B lymphocytes, serving as a Burkitt’s lymphoma model (P493-6), the suppression of a conditional c-MYC allele induces global heterochromatic regions resembling the phenotype described for N-MYC disruption in neuronal progenitor cells." (PMID 28505071, 2017). "Here, we report that in T-cell acute lymphoblastic leukemia (T-ALL) and Burkitt’s lymphoma the MYC oncogene causes overexpression of DNA methyltransferase (DNMT) 1 and 3B, which contributes to tumor maintenance." (PMID 29100357, 2017). "In particular, MYC is associated with hematopoietic malignancies such as Burkitt’s lymphoma and T-cell acute lymphoblastic leukemia (T-ALL)." (PMID 29100357, 2017). "MYC is the proto-oncogene classically associated with Burkitt lymphoma (BL) located at chromosomal locus 8q24." (PMID 28983465, 2017). "In particular, the B-cell malignancy Burkitt’s Lymphoma is associated with reciprocal chromosomal translocations between MYC and one of 3 immunoglobulin loci." (PMID 28398229, 2017). "Activation of MYC gene is considered the main pathogenetic feature of Burkitt lymphoma, but other genetic mutations are also essential for lymphomagenesis." (PMID 26416427, 2015).
Burkitt lymphoma (continued). "Burkitt lymphomas tended to be segregated from the other types of BCLs where MYC was predicted as a mutated gene with altered expression." (PMID 25903198, 2015). "All Burkitt’s lymphomas have chromosomal translocations that place the MYC oncogene under the control of the Ig heavy chain or one of the light-chain loci, which induce MYC deregulation and contribute to the pathogenesis associated with Burkitt’s lymphoma." (PMID 25340830, 2014). "In particular, a signature of 38 miRNAs containing MYC and nuclear factor-κB (NF-κB) pathway-associated miRNAs has been obtained, differentiating Burkitt’s lymphoma from DLBCL." (PMID 25364378, 2014). "It is thus tempting to postulate that MYC overpexression in Burkitt's lymphoma and EBNA3s expression in EBV-associated lymphoproliferations fulfil—via MIZ-1—similar functions important for continuous cell proliferation." (PMID 25092922, 2014). "Over-expression of the proto-oncogene c-MYC is frequently observed in a variety of tumors and is a hallmark of Burkitt ́s lymphoma." (PMID 24130880, 2013). "This phenomenon is frequently described in Burkitt’s lymphoma and is associated with a longer half-life of MYC mRNA in affected cells." (PMID 24053468, 2013). "A MYC gene rearrangement is most frequently associated with Burkitt lymphoma yet has been reported in other mature and immature B-cell neoplasms." (PMID 23533894, 2013). "Burkitt lymphoma is endemic in the Equatorial Belt of Africa, its molecular hallmark is an activated, MYC gene mostly due to a chromosomal translocation." (PMID 22593768, 2012). "Burkitt lymphoma (BL) is a very aggressive subtype of non-Hodgkin lymphoma (NHL) usually associated with translocation of the MYC oncogene." (PMID 22570659, 2012). "Furthermore, two common MYC mutant alleles observed in Burkitt's lymphoma have been shown to uncouple proliferation from apoptosis and are therefore more efficient in inducing B‐cell lymphogensis." (PMID 40488968, 2025). "The pathogenesis of Burkitt lymphoma is closely linked to the translocation of the c-MYC gene." (PMID 41180747, 2025). "Persistent DSBs, may cause deletions and chromosomal abnormalities, including cancer-associated translocations, such as those observed in the human c-MYC gene implicated in Burkitt lymphoma, and other cancers." (PMID 39043652, 2024). "Additionally, loss of function GNA13 mutations are enriched in Burkitt lymphoma (BL), which is defined by MYC translocations and commonly presents with mLN involvement." (PMID 39025963, 2024). "c-MYC translocation is a hallmark of Burkitt lymphoma development." (PMID 37316814, 2023). "Previous studies have indicated that ZDHHC11 and ZDHHC11B play critical roles in maintaining the oncogenic MYC-miR-150-MYB axis in Burkitt’s lymphoma, and ZDHHC11 may be a biomarker to identify high-risk bladder cancer patients with disease progression." (PMID 34490261, 2021). "The constitutive expression of MYC, caused by genomic rearrangement of the gene, is a frequent abnormality and major oncogenic driver in many aggressive hematopoietic malignancies including Burkitt lymphoma." (PMID 30453475, 2018). "This may explain how the virus causes particular changes to the MYC gene that are found in Burkitt’s lymphoma." (PMID 27490482, 2016).